IL10 (interleukin 10)
Diseases named in the same sentence as IL10 in open-access papers (continued):
Sharing a sentence is not in itself a finding about the gene and the disease.
autoimmune disease (continued). "Taken together, these findings show that the loss of HIF-1α in B cells causes impaired IL-10 production and aggravating autoimmune diseases." (PMID 29343683, 2018). "Studies in animal models of autoimmune diseases have shown that intracellular expression of IL-10 is linked to the ability of CD4+LAP+ cells to attenuate disease severity." (PMID 30425718, 2018). "In particular, IL-10 inhibits the production of inflammatory cytokines and is implicated in the pathogenesis of inflammatory and autoimmune diseases." (PMID 29765083, 2018). "Taken together, this study demonstrates the key function of the hypoxia-associated transcription factor HIF-1α in driving IL-10 expression in CD1dhiCD5+ B cells, and in controlling their protective activity in autoimmune disease." (PMID 29343683, 2018). "Genetic mutation in IL-10 is linked to autoimmune diseases in human and mice that loss of IL-10 develops severe RA inflammation and augments disease progression." (PMID 28415811, 2017). "Autoimmune disease models in IL-10-deficient mice have helped elucidate the role of this cytokine in T cell homeostasis in the periphery." (PMID 28316998, 2017). "An association between the polymorphisms of IL-10 gene and various inflammatory and autoimmune diseases including Juvenile Rheumatoid Arthritis, Behcet’s disease, non-infectious uveitis, and Type 1 diabetes have been reported." (PMID 28257625, 2017). "Since immunity and susceptibility to autoimmune disease is well-known to be influenced by age and gender, we analyzed the IL-10 response in CD4+ T cells from both male and female mice within an age range from 7 to 18 weeks." (PMID 28742882, 2017). "This is the first report of the positive effect of the consumption of SDA-rich dietary oil on IL-10, an anti-inflammatory cytokine displaying a deficiency in human autoimmune diseases." (PMID 28287415, 2017). "Subsequent studies have shown that CD1dhighCD5+ B cells were associated with the suppression of inflammation and autoimmune disease through IL-10 secretion." (PMID 28243231, 2017). "Suppression of IL-10 expression can enhance inflammatory response to microbial challenge but also increase the risk of developing a number of autoimmune diseases." (PMID 29190740, 2017). "A deficiency of IL-10 is associated with the development of spontaneous colitis in mice and a number of autoimmune diseases." (PMID 27584662, 2016). "The dysregulation of IL-10 is associated with an enhanced immunopathologic response to infection, as well as with an increased risk for developing numerous autoimmune diseases." (PMID 27584662, 2016). "Genetically determined defects in IL-10 production and IL-10R signaling would be downstream of a calcitriol-mediated increase in Tr1 cells; both defects were linked to an increased autoimmune disease risk." (PMID 25852682, 2015). "Thirdly, a detailed medical history was not obtained from the participating children, thus other condition causing increased IL-10 levels such as asthma, bacterial infections, viral infections, and autoimmune diseases, cannot be excluded." (PMID 25888883, 2015). "Mice with IL-10 knocked out developed more severe lupus, an autoimmune disease mediated by pathogenic Th1 cytokine responses." (PMID 24788117, 2014). "IL-10-producing B cells are known to be critical for suppression of autoimmune diseases, although B cells are both pathogenic and protective in autoimmune diseases." (PMID 25136147, 2014). "This IL-10 cytokine family member plays both protective and pathogenic roles in autoimmune diseases but its involvement in MS is still matter of debate." (PMID 25411844, 2014). "IL-10 has been implicated to play a critical immunosuppressive role in autoimmune diseases, including RA." (PMID 24742125, 2014). "Expression of TLR1, TLR2, TLR4, TLR7 and TLR9 transcripts has been reported on B cells, and TLR-activated B cells are capable of resolving autoimmune disorders by inhibiting pathogenic T cells via IL10 production." (PMID 23755918, 2013).
autoimmune disease (continued). "Diverse disorders such as asthma and autoimmune diseases associated with Westernized living are widely believed to result from insufficient levels of IL-10 and insufficient immune calibration essential for sustained systemic health." (PMID 23874682, 2013). "The cytokine IL-10 and its family members have been implicated in autoimmune diseases and we have previously reported that genetic variants in IL-10 were associated with a rare group of diseases called juvenile idiopathic arthritis (JIA)." (PMID 23094074, 2012). "Low levels of IL10 production associated with autoimmune disease, such as rheumatoid arthritis, psoriasis, and collagen-induced arthritis, suggest defective regulatory roles of IL10 in limiting inflammation and reversing immunopathology." (PMID 16959027, 2006). "B cells exhibit dual immunomodulatory functions in T-cell-mediated autoimmune diseases, demonstrating both protective effects through regulatory cytokine secretion (e.g., IL-10) and pathogenic contributions via proinflammatory mediators (including TNF-α, IL-6, and GM-CSF)." (PMID 40691766, 2025). "Research in mice further indicates that IL-10 production may play a protective role in organ-specific autoimmune diseases by regulating the balance between pathogenic Th1 cells and protective, anti-inflammatory Th2 cells." (PMID 40160814, 2025). "However, the dysregulation of IL-10 is associated with enhanced immunopathology in response to infection as well as increased risk for development of autoimmune diseases." (PMID 38399674, 2024). "Several autoimmune disorders have been linked to polymorphisms in IL10 and IL6R genes." (PMID 38822340, 2024). "Dysfunction of interleukin-10 producing regulatory B cells has been associated with the pathogenesis of autoimmune diseases, but whether regulatory B cells can be therapeutically induced in humans is currently unknown." (PMID 37045832, 2023). "IL-10 is considered an antagonist to these pro-inflammatory cytokines exerting immunosuppressive functions and dysregulation or deficiency is often associated with autoimmune diseases and chronic infections." (PMID 36862362, 2023). "This discrepancy could be linked to the time course of IL-10 secretion, with peak levels occurring 7–14 days after the initiation of various experimental autoimmune diseases." (PMID 37511839, 2023). "Moreover, dysregulation of IL-10 has been associated with an enhanced risk for the development of autoimmune diseases." (PMID 36232593, 2022). "Besides the expansion of pathogenic Th17 cells, autoimmune diseases are classically associated with impaired production of the anti-inflammatory cytokine IL-10 by regulatory CD4+ T cells." (PMID 35109870, 2022). "In addition to these antibodies known to be associated with autoimmune diseases, other antibodies such as autoantibodies against type I-IFNs or directed against other cytokines including GM-CSF, IL-6, and IL-10 have also been identified." (PMID 35453524, 2022). "IL-10 is associated with many autoimmune diseases due to its anti-inflammatory functions." (PMID 36009467, 2022). "IL-10 family members are essential anti-inflammatory cytokines with immunosuppressive actions that promote epithelial homeostasis and barrier function in response to infection or inflammatory conditions, while IL-10 deficiency is involved in autoimmune disorders." (PMID 34439323, 2021). "Previous studies demonstrated that a deficiency in IL-10 induces autoimmune disease, including a wide range of experimental models, such as experimental autoimmune neuritis, systemic lupus erythematosus, experimental autoimmune encephalomyelitis, and rheumatoid arthritis." (PMID 35053004, 2021). "As proinflammatory cytokines are mainly secreted by Tregs, the decrease in IL-10 secretion might indicate impaired Treg suppressive function, which could also contribute to a higher risk of autoimmune diseases." (PMID 33790890, 2021).
autoimmune disease (continued). "Il-10 secreting T cells in particular have been associated with protection or recovery from allergies and autoimmune disease and may in vivo include both tTreg and Tr1 subsets." (PMID 34262557, 2021). "Effective removal of damaged cells reduces the risk of necrosis and inflammation, and by binding of apoptotic cells to the phosphatidylserine receptor, many immunosuppressive cytokines (TGF-β, PGE2, PGI2, and IL10) are released to suppress inflammation and reduce the risk of autoimmune diseases." (PMID 34204341, 2021). "Over production of il-10 is associated with enhanced immunopathology and immunosuppression in response to several parasitic diseases in humans as well as an increased risk factor for development of autoimmune disease." (PMID 32582181, 2020). "IL-10 is a well-known anti-inflammatory cytokine that plays crucial roles in improving host immune response against pathogenic invaders and preventing inflammatory and autoimmune diseases." (PMID 31001563, 2019). "IL‐10‐producing B cells (B10) are associated with autoimmune diseases, infection and tumours." (PMID 30467955, 2019). "In addition, the gene expression, the receptor structure, the associated gene polymorphisms, and the signaling pathway of IL-10 are all associated with the development of autoimmune diseases." (PMID 31240224, 2019). "Wild-type CD1dhiCD5+ B cells, but not Hif1a-deficient CD1dhiCD5+ B cells, protect recipient mice from autoimmune disease, while the protective function of Hif1a-deficient CD1dhiCD5+ B cells is restored when their defective IL-10 expression is genetically corrected." (PMID 29343683, 2018). "We next used a similar genetic approach to test whether the suppressive defect of Hif1a-deficient CD1dhiCD5+ B cells in autoimmune disease could similarly be rescued by genetically ecotopic-expressing IL-10." (PMID 29343683, 2018). "Impairment of IL-10 is associated with high risk for development of many autoimmune diseases." (PMID 28455817, 2017). "However, IL-10 deficiency in mice results in autoimmune disease in the intestinal tract driven by unimpeded reactivity of effector CD4+ T cells to antigens of intestinal microorganisms." (PMID 28810829, 2017). "In humans, IL-10+Breg cells are decreased in active autoimmune diseases, such as rheumatoid arthritis, ANCA-associated vasculitis, and systemic sclerosis, and may increase to normal levels in disease remission." (PMID 32185261, 2017). "Indeed, IL-10 deficiency aggravates several experimental autoimmune disorders, illustrating the central role of this cytokine in immune regulation." (PMID 28316998, 2017). "Patients with autoimmune disease or autoimmune enteropathy, including those with immunodysregulation, polyendocrinopathy, enteropathy, X-linked syndrome, defects in interleukin-10 (IL-10) signaling pathways, gain-of-function STAT-3 disease, and CTLA-4 deficiency, have received curative transplants." (PMID 26918153, 2015). "IL-10-deficient mice exhibit prolonged inflammatory responses under a variety of experimental conditions, whereas in humans the levels of IL-10 inversely correlate with the severity of autoimmune diseases." (PMID 25884400, 2015). "IL-10 is considered an immunosuppressive modulator acting on a number of innate and adaptive immune cells and deletion of the IL-10 gene can render mice more susceptible to infection pathology or autoimmune disease." (PMID 24587458, 2014). "In addition, IL-10 was believed to be a potent anti-inflammatory cytokine and ablation of IL-10 exacerbates autoimmune diseases, however, current evidence suggests that IL-10 deficiency does not accelerate T1D in NOD mice." (PMID 24629100, 2014). "Polymorphisms in the IL-10 gene may alter IL-10 production, and thus influencing susceptibility to autoimmune diseases." (PMID 23936042, 2013).
autoimmune disease (continued). "IL-10, although traditionally considered an anti-inflammatory cytokine, has also been implicated in promoting abnormal angiogenesis in the eye and in the pathobiology of autoimmune diseases, such as lupus and encephalomyelitis." (PMID 23201926, 2012). "Interleukin-10 (IL-10), although traditionally considered an anti-inflammatory cytokine, has also been implicated in promoting abnormal angiogenesis in the eye and in the pathobiology of autoimmune diseases such as lupus and encephalomyelitis." (PMID 19771172, 2009). "IL-10 is an immunomodulatory cytokine generated by multiple cell types with potent anti-inflammatory and immune-suppressive effects, and its deficiency may cause autoimmune disease." (PMID 41441001, 2025). "For example, pharmacological blocking of Il10 using antibodies, decoy receptors or small molecules administered peripherally could carry the unintended risk of autoimmune diseases of the gut, hepatic damage in patients with chronic infection and general immunologic anergy." (PMID 40055831, 2025). "Although IL-10 is known as a potent anti-inflammatory cytokine and has been emphasized in Breg cell-related therapy, excessive IL-10 levels may lead to immune disorders and increase the risk of autoimmune diseases by disrupting the immune balance and regulating the activation of immune cells." (PMID 40385489, 2025). "Moreover, IL-10 deficiency exacerbates T-cell-mediated autoimmune diseases." (PMID 39436890, 2024). "IL-10, which has anti-inflammatory properties and can help regulate the immune response, was restored in proportion to concentration by all postbiotics, demonstrating their potential in improving IL-10 dysregulation associated with the risk of developing many autoimmune diseases." (PMID 38921035, 2024). "Interleukin 10 (IL-10) is a potent anti-inflammatory cytokine whose deficiency or abnormal expression may increase the inflammatory response or lead to the development of a number of autoimmune diseases." (PMID 35805112, 2022). "Several molecules produced by B cells, such as IL-10 and IL-35, as well as an increased function of B cells as antigen-presenting cells (APCs), were associated with higher activation of macrophages and pro-inflammatory T cells in MS and other autoimmune diseases." (PMID 34359880, 2021). "We also show that suppression of EAU pathology in CD4-IRF4KO correlates with expansion of IL-10-producing (Treg) or IL-35-producing (iTR35) T cells and production of these immune-suppressive cytokines play critical roles in downregulating immune responses that cause autoimmune diseases." (PMID 33803441, 2021). "In the current paper, we investigated whether immunizing mice using TLR4 ligand as adjuvant and 2 different antigens (HPV16 E7 peptide, soluble antigen OVA), and simultaneously blocking IL-10 signalling would lead to inflammation in the gut and cause autoimmune disease." (PMID 28810829, 2017). "However, IL-10 deficiency leads to autoimmune disease in the gut." (PMID 28810829, 2017). "Importantly, both subsets can produce IL-10, but provide help to B cells in the production of IgG, and could play a pathogenic role in autoantibody-driven autoimmune disease." (PMID 28526072, 2017). "Moreover, IL10-knockout animals are more susceptible to the development of autoimmune diseases." (PMID 25826263, 2015). "Of note, in patients with autoimmune diseases the total IgM pool may be enriched in Abs produced by short-lived PC, since the overexpression of IL-10 and CD154, detected in some patients, have been associated to a rapid PC differentiation and auto-Ab production." (PMID 24819618, 2014). "Therefore the evidence suggests that IL-10 deficiency or alteration could be more important as an etiologic factor in autoimmune diseases than in immunodeficiencies." (PMID 16803619, 2006). "Regulatory B cells (Bregs) secrete IL-10 to suppress the human immune system, resulting in the control of some autoimmune diseases." (PMID 41208111, 2025).
autoimmune disease (continued). "Bregs are a unique type of B cell that produce IL-10 to suppress proinflammatory immune responses and are necessary for the proper control of autoimmune disorders." (PMID 41208111, 2025). "Strategies are being developed to improve the stability and delivery of IL-10 derivatives to effectively modulate the immune balance in autoimmune diseases such as rheumatoid arthritis and inflammatory bowel disease." (PMID 41376630, 2025). "Therapies aiming at restoring IL-10 levels are already widely being investigated for autoimmune diseases." (PMID 40276034, 2025). "The potential of IL-10 agonism in the treatment of autoimmune disease has been explored but is limited due to off-target effects." (PMID 40069219, 2025). "For example, certain microbial metabolites can influence the secretion of cytokines such as IL-10 and IL-17, further modulating the Treg/Th17 ratio and thereby affecting the progression of autoimmune diseases." (PMID 41293163, 2025). "In autoimmune diseases, like ankylosing spondylitis, increased levels of IL-10 in the serum have been described." (PMID 40881695, 2025). "Together, our findings identify R1-EVs as dual-functions, DX- and IL-10-dependent nanoplatform that integrates antioxidant and tolerogenic properties, with potential applications in inflammatory and autoimmune disease control." (PMID 41009012, 2025). "At the same time, IL-10 stimulates proliferation, B lymphocyte differentiation, and antibody secretion and participates in the pathogenesis of autoimmune diseases such as systemic lupus erythematosus." (PMID 41155393, 2025). "Regulatory B cells that secrete IL-10 are called B10 cells and have the functionality to inhibit inflammatory damage in autoimmune diseases." (PMID 39949783, 2025). "IL-10-producing Breg cells (B10 cells) are particularly important in the regulation of autoimmune diseases." (PMID 39949783, 2025). "Due to its potent anti-inflammatory properties, IL-10 holds great promise for therapeutic applications in inflammation, cancer and autoimmune diseases." (PMID 41376630, 2025). "IL-10 is known to counteract excessive immune responses and inflammation, playing a critical role in maintaining immune homeostasis and preventing autoimmune diseases and local toxicity." (PMID 39432476, 2024). "Given its ability to suppress inflammatory responses, IL-10 is being investigated as a potential therapeutic agent for autoimmune diseases such as rheumatoid arthritis, psoriasis, inflammatory bowel disease (IBD), and multiple sclerosis." (PMID 38248028, 2024). "Interleukin-10 (IL-10) is a cytokine with a dual role in tissue homeostasis and autoimmune diseases." (PMID 39541341, 2024). "Together, Bregs have been shown to modulate immune responses to cancer, infections, autoimmune diseases via production of IL-10." (PMID 39346706, 2024). "IL-10: As an anti-inflammatory cytokine, IL-10 has been explored in various clinical contexts, including autoimmune diseases such as Crohn’s disease and rheumatoid arthritis." (PMID 39772057, 2024). "Multiple research projects indicate the essential roles of IL‐6, IL‐10, IL‐21, and IL‐17 in the pathogenesis of autoimmune diseases." (PMID 36271684, 2024). "In our research, ten SNPs covering IL10 and IL6R genes were chosen based on previous association studies of autoimmune disorders, such as IBD, RA, MS and AS." (PMID 38822340, 2024). "IL-10 plays a pleiotropic role in many autoimmune diseases, organ transplantation, and tumor tolerance, including via Treg-mediated suppression." (PMID 39351218, 2024). "The pleiotropic nature of IL-10 presents a unique advantage for CAR T cell therapy in autoimmune diseases." (PMID 39697333, 2024). "Interleukin-10 (IL10) act as an anti-inflammatory cytokine that modulates immune response in autoimmune diseases including psoriasis and uveitis." (PMID 38822340, 2024).